BRD4 (bromodomain containing 4)
Diseases named in the same sentence as BRD4 in open-access papers (continued):
Sharing a sentence is not in itself a finding about the gene and the disease.
cancer (continued). "An analysis of human disease revealed that in addition to participating in the cancer pathway, most of the genes bound to BRD4 are associated with infectious and immune-related diseases." (PMID 39349832, 2024). "NUT carcinoma, a rare but highly malignant cancer, is caused by genomic rearrangements involving the BRD4 or BRD3 and Nuclear Protein in Testis (NUT) genes." (PMID 38539439, 2024). "Another mechanism of resistance is connected with the suppression of the PRC2 complex, which involves the activation and recruitment of WNT-signaling components to compensate for the loss of BRD4 and drive resistance in various cancer models." (PMID 37190100, 2023). "Clinically, BRD4 acts as a chromatin-binding protein implicated in cancer and autoimmune/infectious diseases that functions as a scaffold for transcription factors at promoters and super-enhancers." (PMID 37509171, 2023). "Perhaps most importantly, BRD4 has been implicated in cancer aggression through promoting angiogenesis, a process highly dependent on actin, making bet-1/BRD4 a highly promising candidate for understanding the mechanistic role of actin during aging." (PMID 37204421, 2023). "The mammalian bromodomain and extra-terminal domain (BET) family of proteins consists of four conserved members (Brd2, Brd3, Brd4, and Brdt) that regulate numerous cancer-related and immunity-associated genes." (PMID 37049806, 2023). "BRD4 dysfunctions are associated with multiple diseases such as cancers, neuro-degenerative disorders, autoimmune diseases, and heart, kidney, lung, and inflammatory diseases." (PMID 36902175, 2023). "Cancer cells compensate for the loss of bromodomain transcriptional activity by upregulating BRD4 downstream pathways, such as Wnt/β-catenin, Hedgehog, and RAS-RAF-MAPK, which restore Myc expression." (PMID 36902175, 2023). "BRD4 also plays a role in regulating the cell cycle, and abnormal expression of BRD4 has been associated with various types of cancers and other diseases." (PMID 37461108, 2023). "In TALL cancer cells and during thymocyte development in vivo, certain patterns of alternative splicing are linked to BRD4 depletion." (PMID 37509171, 2023). "These inhibitors are primarily used to disrupt the interaction between BRD4 and acetylated histones, which can lead to the downregulation of specific genes associated with cancer." (PMID 38201534, 2023). "Among the cancer-associated proteins whose expression is downregulated by small molecule BRD4 inhibitors are the oncogenic driver c-Myc, the anti-apoptotic Bcl2, and cell cycle regulators such as the cyclin-dependent kinases." (PMID 36768967, 2023). "BRD4 has been implicated in a broad spectrum of human cancers and is increasingly appreciated as a promising anticancer target, including SCLC." (PMID 35453346, 2022). "In cancer, BRD4 has been implicated in the activation of a multitude of oncogenes, co-occupying a set of promoter super-enhancers associated with prominent oncogenic drivers such as c-MYC." (PMID 35681619, 2022). "These dysregulated transcriptional programs can cause cancer cells to become highly dependent on transcriptional regulators, such as Mediator and BRD4." (PMID 35740532, 2022). "In particular, de-regulation of BRD4 has been associated with several cancer types, and BET inhibitors are potential drugs for anti-cancer and immune diseases." (PMID 35157728, 2022). "BRD4 is an epigenetic reader that has been implicated in the regulation of the development and progression of various cancers." (PMID 35902869, 2022). "BRD4 is also a drug target in cancers with aberrant SWI/SNF function, caused by mutated SWI/SNF subunits BRG1 or BRM." (PMID 35182012, 2022). "Recently, our lab reported that high expression of BRD4 in T-ALL cell lines in the Cancer Cell Line Encyclopedia database was associated with poor prognosis of patients with T-ALL in The Cancer Genome Atlas (TCGA) database." (PMID 35832114, 2022).
cancer (continued). "In T-cell acute lymphoblastic leukemia (T-ALL) cancer cells and during thymocyte differentiation in vivo, distinct patterns of alternative splicing are associated with BRD4 deletion." (PMID 34540900, 2021). "Among bromodomain and extra terminal (BET) proteins (BRD2, BRD3, BRD4), BRD4 has been strongly linked to cancer and inflammatory diseases, thereby representing an attractive target." (PMID 33959589, 2021). "Altogether, these data suggest that BET inhibitors and more specifically BRD4 inhibitors are interesting leads to induce BRCA-deficiency in cancer cells." (PMID 34208195, 2021). "MYC is one of the most studied oncogenes in HGSOC, which has been often associated with BRD4, and whose expression in cancer can be down regulated by BETi." (PMID 34758842, 2021). "This analysis linked the BRD4-regulated network with epithelial carcinoma–driven states, consistent with its role in oncogenesis." (PMID 34765643, 2021). "BRD4 has long been implicated in many different pathological processes, in particular, the development of cancer and inflammation." (PMID 32303673, 2020). "BRD4 has been implicated in cell proliferation, metastasis, and prognosis in several types of cancer." (PMID 32499570, 2020). "CDK1 over-activation frequently observed in cancers has the potential to cause aberrant BRD4 hyperphosphorylation persisting outside of mitosis to strengthen its target gene binding and confer BETi resistance." (PMID 32575711, 2020). "BRD4, a gene that is overexpressed in different human cancers, is associated with carcinogenesis, tumorigenesis, and progression of human malignancies." (PMID 32978368, 2020). "Dysregulation of BRD4′s activity has been implicated in the pathogenesis of a wide variety of cancers." (PMID 32575711, 2020). "Our study therefore suggests that CDK1 inhibition can be employed to overcome tumor BETi resistance and improve treatments for BRD4-associated cancers." (PMID 32575711, 2020). "Taken together, BRD4 appears to be an oncogene in various cancers and is associated with the progression of cancer metastasis." (PMID 31621555, 2020). "Based on this finding, it will be interesting to investigate how aberrant CDK1 activation in cancer cells can be explored as a therapeutic target for treating BRD4-associated cancers." (PMID 32575711, 2020). "Studies have shown that ARV-825 is far more efficient than the small molecule BRD4 inhibitors in suppressing BRD4 signaling, causing potent and sustained cancer cell inhibition and profound apoptosis induction." (PMID 32163373, 2020). "We report that deregulated transcription following BRD4 loss in cancer cells leads to the accumulation of RNA:DNA hybrids (R-loops) and collisions with the replication machinery causing replication stress and DNA damage." (PMID 32796829, 2020). "ZNF532 encodes a protein that prominently interacts with the BRD4-NUT interacting fusion oncoprotein in the chromatin of NUT midline carcinoma cells and drives oncogenesis by propagating the oncogenic chromatin complex." (PMID 32644941, 2020). "The epigenetic reader protein Brd4 has been implicated in various cancers, including medulloblastoma." (PMID 31292434, 2019). "We used public databases to investigate BRD4 expression in cancer tissues and its association with the prognosis of cancer patients." (PMID 30988278, 2019). "In summary, BRD4 expression is higher in cancer tissues than in normal tissues and is positively associated with more severe subtypes and stages." (PMID 30988278, 2019). "Immunohistochemical expression of BRD4 in cancer cells was also shown to be associated with T-bet+ TILs (p = 0.0415) as well as with Jagged1 mRNA and protein expression (p = 0.0171, 0.0010 respectively)." (PMID 30029633, 2018). "Recently, they have also been implicated in transcriptional dysregulation in many cancer types, with BRD4 identified as a key player in AML." (PMID 29527516, 2018).
cancer (continued). "BRD4 has been implicated in a number of studies for its role in promoting inflammation notably via activating NF-kB-regulated pathways in cancer cells." (PMID 30029633, 2018). "It has been reported that BRD4 is associated with a variety of cancers due to its role in the regulation of cell cycle progression." (PMID 28545522, 2017). "The BET proteins are widely associated with cancer progression, as it was demonstrated that BRD4 has the ability to associate with positive transcription elongation factor b (P-TEF-b) to promote the G1-S transition of the cell cycle." (PMID 27006472, 2016). "The object of this study were three of the four BET proteins BRD2, BRD3 and BRD4 and to our knowledge, this is the first spectroscopic characterization in solution of human BRDs variants found in cancer." (PMID 27403962, 2016). "In addition, hyperphosphorylation of BRD4 has been implicated in the long-term resistance of cancer cells (e.g., NUT midline carcinoma) to BBDi." (PMID 40149571, 2025). "For example, a photocaged PROTAC against BRD4 was designed in an inactive form and activated with light and a caged ligand, thereby causing the rapid degradation of BRD4, one of the most important epigenetic regulators involved in cancer development." (PMID 41362117, 2025). "Furthermore, our pan-cancer analysis revealed a significant association between BRD4 expression and metastasis and survival, underscoring the involvement of BRD4 and IGF2BP3 in tumor progression across various cancer types." (PMID 40162116, 2025). "BRD4 overexpression has been previously linked with the suppression of cancer cell growth in selected human and mouse cell line models, but it has not been attributed to the toxicity profile we observed when systematically interrogating the effects of gene overexpression across multiple tumor types." (PMID 40112818, 2025). "Generally, BRD4 controls genes involved in cell cycle progression and lineage allocations by chromatin remodeling and transcriptional regulation, and its aberrant activity is implicated in various types of cancers." (PMID 38874522, 2024). "This transcriptional activity is associated with the bromodomain-containing factor BRD4, which also binds to acetylated lysine-310 of the subunit RelA (p65) of the activity of transcription factor NFκB, maintaining persistently active NFκB in malignant tumors." (PMID 39201306, 2024). "Furthermore, triptolide has been investigated to modulate cancer gene expression via epigenetic downregulation of genes associated with super-enhancers (e.g., BRD4, MYC, RNA Pol II)." (PMID 39163135, 2024). "In vitro studies have demonstrated that ARID1A deficiency could sensitize cancer cell lines to PARPi, BRD4 inhibitor and EZH2 inhibitor." (PMID 39104720, 2024). "Consequently, there are potential clinical implications of BRD4 inhibition in Gq‐mutated cancer cell subpopulation." (PMID 37994501, 2023). "BRD4 regulates cancer cell migration and invasion and is associated with poor clinical outcomes." (PMID 37737256, 2023). "BET proteins, and in particular BRD4, have been implicated in human disease especially cancer." (PMID 36711038, 2023). "Hyperphosphorylation of BRD4 is often associated with an increased activity that could be found in the breast, colorectal, small-cell lung, pancreatic, and many other cancers." (PMID 37509171, 2023). "Moreover, BRD4 has been implicated in cancer aggression as an angiogenesis promoting factor, a process that directly involves actin polymerization." (PMID 36404134, 2023). "Given the multifaceted roles of BRD4, combinations of BRD4 inhibitors with other drugs have showcased advantages, including potent therapeutic effects, wide safety index and reduced susceptibility to drug resistance in cancer treatments." (PMID 38099141, 2023).
cancer (continued). "BRD4 is important for a variety of cellular functions involving cell cycle progression, DNA damage response, and inflammation, which has been associated with the development of several diseases, including cancer and inflammatory disorders." (PMID 37765111, 2023). "Next, we investigated whether aminocyclopropenone compounds attenuate the phase separation ability of BRD4, which is a determinant of the aberrant transcriptional activity underlying cancer cell growth." (PMID 35159127, 2022). "In addition to controlling expression of key oncogenes, BRD4 mutations have also been documented in several cancers." (PMID 36077617, 2022). "However, dysregulation of Brd4 has been linked to variety of human diseases, including cancer, immune disorders, and metabolic diseases." (PMID 36539410, 2022). "Interestingly, the possible oncogenic role of the BRD4–SWI/SNF interaction extends to far more cancer types than those caused by FET oncoproteins." (PMID 35182012, 2022). "BRD4 is the best studied subtype that has been implicated in various human cancers." (PMID 35458687, 2022). "BRD4-gene rearrangements and mutations have been documented in a number of human cancers." (PMID 35226658, 2022). "BRD4 is the most well-studied and has been implicated in various human cancers." (PMID 36224471, 2022). "Recent evidence suggests BRD4 functions in DNA damage repair and DNA damage checkpoint that may be linked to cancer development." (PMID 35681734, 2022). "BET and, in particular, BRD4 have been implicated in human diseases, especially cancer." (PMID 34681760, 2021). "A high expression of BRD4 in cancer tissues has been associated with poor prognosis." (PMID 33947836, 2021). "BRD4 has been shown to occupy the enhancers of actively transcribed genes, particularly at large super-enhancer regions that are associated with the expression of transcription factors and other genes that drive cancer and tissue-specific cell development." (PMID 33712563, 2021). "The synergistic effect of the CDK1 inhibitor and BETi observed in our studies therefore provides the rationale for exploring aberrant CDK1 activation in cancer cells as a therapeutic target to overcome tumor BETi resistance and improve treatments for a diverse array of BRD4-associated cancers." (PMID 32575711, 2020). "Aberrant BRD4 function has been implicated in the pathogenesis of a wide range of cancers." (PMID 32575711, 2020). "BRD4 is the most researched member of this family and is associated with multiple human cancers." (PMID 33135348, 2020). "BETs, and in particular BRD4, have been implicated in human disease, especially cancer." (PMID 30554943, 2019). "In addition, BRD4 has been shown to regulate molecular mechanisms related to the repair of damaged DNA and to be implicated in aberrant telomere regulation in cancer, highlighting the diversity of functions of this protein in carcinogenesis." (PMID 30841549, 2019). "We discovered that BRD4 expression was higher in cancer tissues than in normal tissues and was associated with poorer prognoses in cancer patients, indicating that targeting BRD4 may confer a clinical benefit in cancer patients." (PMID 30988278, 2019). "The relevance of BRD4 in controlling TERT expression selectively in presence of cancer-associated promoter mutations, seems to suggest that inhibition of BRD4 by BETi could represent an alternative and more selective inhibition of telomerase." (PMID 30466442, 2018). "In such environment, inhibition of BRD4 has greater consequences that on regular ENHs conferring to SE-associated genes a higher magnitude of susceptibility to BETi and explaining at least in part the cancer selective activity of these drugs." (PMID 30466442, 2018). "However, cancer associated genes seem to be selectively dependent on BRD4 being c-MYC the paradigm of this model." (PMID 30466442, 2018). "In BRD4-dependent cancers, the antitumor efficacy of JQ1 is associated with G1 cell-cycle arrest." (PMID 22901802, 2012).
cancer (continued). "It has been shown that BRD4 proteins are involved in the development of a variety of cancers, and their alterations are considered to be an important oncogenic driver that causes or maintains malignant growth, so BRD4 has become an attractive cancer therapeutic target." (PMID 40078291, 2025). "However, the occurrence of mutations in BRD4 specifically has been reported to be low in cancers." (PMID 29296220, 2017). "However, while MEK and BRD4 inhibitors converge in the downregulation of genes associated with cancer-acquired super-enhancers, NSD2 inhibition affects the expression of clusters of genes embedded in megabase-scale regions marked with H3K36me2 and that contribute to the RAS transcription program." (PMID 27604143, 2016). "Considering its role in oncogene regulation, BRD4 has become a crucial target for cancer therapy, resulting in the development of multiple BET inhibitors." (PMID 41614901, 2026). "Bromodomain and extraterminal motif (BET) inhibitors, such as JQ1, are promising cancer therapeutics that target epigenetic regulators, particularly BRD4." (PMID 42069518, 2026). "PROTAC degrades BRD4 selectively in several cancer cell lines, resulting in an accurate hypoxia-dependent activity in living cells, zebrafish, and mice with solid tumors." (PMID 41012497, 2025). "In CRC, superenhancers are enriched not only for BRD4 but also for other proteins, such as the coactivator Mediator, which cooperates with BRD4 in sustaining the expression of cancer-acquired superenhancer genes (e.g., MYC)." (PMID 41311847, 2025). "It has been reported that MED12 functions in maintaining cancer cell proliferation, along with BRD4." (PMID 40888963, 2025). "Loss of bromodomain containing 4 (BRD4) can inhibit many cellular events to reduce the accumulation of R-loops, and has proved useful in the treatment of cancers." (PMID 40061014, 2025). "Owing to its high expression in LUAD, which correlates with the malignancy of cancer cells and poor prognosis, BRD4 is considered a potential therapeutic target." (PMID 40083325, 2025). "The discovery of BRD4 as a potential target for cancer treatment is one instance of a successful therapeutic target discovery using CRISPR." (PMID 41394966, 2025). "JQ1, a potent inhibitor of BET activity (including BRD4), effectively combats cancer by weakening enhancer activity, particularly SEs 38,67." (PMID 40631184, 2025). "Ongoing studies are also assessing the advantage of combined therapy of BRD4 inhibitors and Stat3 blockers or BRD4 inhibitors with chemotherapy over monotherapy in suppressing cancer growth." (PMID 41311847, 2025). "JQ1 inhibits HMT expression called G9a, reducing H3K4me3 abundance of BRD4, and finally induces ferroptosis in cancer cells." (PMID 40327848, 2025). "Reflecting the close association of CDK9 and BRD4 and their interplay in transcriptional regulation, co-targeting CDK9 and BRD4 has been found to elicit synergistic effects in multiple cancer types." (PMID 40163908, 2025). "In turn, BRD4 binds to enhancers, inducing chromatin remodeling and supporting the transcriptional mechanisms within cancer cells." (PMID 40032852, 2025). "This insight into the regulatory role of BRD4 further underscores the potential of targeting chromatin regulators in precision cancer therapy." (PMID 40308947, 2025). "BRD4 expression is higher in cancers than in normal tissues and is correlated with poor overall survival." (PMID 40762981, 2025). "We additionally leverage functional genomic tools to assess the cellular effect of dysregulated BRD4 expression across multiple human cancer cell lines." (PMID 40112818, 2025). "Prior studies have documented that BRD4 inhibitors have substantial anticancer properties across different cancer types, including OSCC." (PMID 39941011, 2025). "Here, we focused solely on ARV-825 and its contribution to BRD4 degradation due to its significant role in cancer cell survival and proliferation." (PMID 40649963, 2025).